TLR5 (toll like receptor 5)
Diseases named in the same sentence as TLR5 in open-access papers (continued):
Sharing a sentence is not in itself a finding about the gene and the disease.
infection (continued). "One obvious reason shorter flagellar filaments may be advantageous for some polar flagellates is in avoiding innate immunity upon infection of hosts where flagellin is an agonist recognized by TLR5 of host cells." (PMID 40788104, 2025). "TLR5 is frequently related with the recognition of H. pylori flagellin, but it seems that this bacterium has developed mechanisms to escape this recognition representing an important factor involved in the persistence of this infection." (PMID 40362298, 2025). "Regarding bacterial recognition receptors, tlr1, which recognizes bacterial lipoproteins, showed decreased expression following infection, whereas tlr5, responsible for detecting bacterial flagellin, increased, peaking at 24 hpi before returning to baseline levels by 48 hpi." (PMID 41256851, 2025). "Moreover, it also hijacks host signaling pathways via its secreted flagellin during infection, which directly binds to its receptor TLR5 on cells in mucosal tissues and then activates immune cells to induce the expression of pro-inflammatory cytokines." (PMID 39533418, 2024). "For example, the importance of the host’s response to flagellated microbes is evident in mice deficient in either TLR5 or NLRC4, which because of their inability to effectively detect flagellin are more susceptible to basal inflammation and infection by enteric pathogens." (PMID 35401545, 2022). "For example, TLR5 found on airway epithelium can recognize Pseudomonas aeruginosa, which is a Gram-negative bacterium that can cause severe infection." (PMID 35986268, 2022). "Addition of purified proteins, bacterial suspensions of L. pneumophila mutant strains as well as supernatants of human lung tissue explant infection to this reporter cell line demonstrated that ProA specifically decreases the TLR5 response via FlaA degradation." (PMID 35625552, 2022). "It was suggested by the lowest energy score of Vaccine-TLR5 complexes respectively, from a molecular docking suggested that the vaccine could have infection-inhibiting activity and might interact tightly with these receptors." (PMID 35939149, 2022). "We speculate that flagellin-induced TLR5 activation plays an important role in the host response to infection with V. anguillarum." (PMID 34912344, 2021). "Alternatively, considering the reproductive imperative to prevent infection of the uterus, TLR5 agonism could lead to changes in mucin production in the cervix to reinforce a mechanical barrier to invasion; mucin could be a nutrient source for these bacteria." (PMID 33199356, 2021). "In our study HIF-1α protein was induced in response to infection with P. histicola (in hypoxic conditions) mediated by TLR5, suggesting that TLR5 in addition to inducing inflammation may also have a regulatory role in the inflammatory response through HIF-1α." (PMID 33031374, 2020). "However, in cells transfected with siRNA targeting TLR5, HiF-1α was significantly reduced in response to infection with P. histicola (30 min, p<0.001) suggesting that P. histicola induced TLR5 signalling was mediated by HIF-1α." (PMID 33031374, 2020). "Bacterial flagella are also known to modulate the immune response during the response to infection, through binding of the major flagellar subunit, flagellin, to TLR5, which triggers TLR-dependent signalling and activates expression of pro-inflammatory cytokines." (PMID 30946644, 2020). "Our results revealed that the mutant lacking BtrS fails to suppress flagella expression and induces robust protective immunity that is TLR5-dependent, suggesting that the careful regulation of potential immunostimulants is critical for successful infection and persistence." (PMID 31889098, 2019).
infection (continued). "The activation of TLR5 by flagellin might play a critical role in inflammatory cytokine responses against B. pseudomallei infection in the initial phase of infection." (PMID 29902230, 2018). "Thus, flagellum synthesis is suppressed at the primary site of infection to avoid immune recognition by either Toll-like receptor 5 (TLR-5) or the NRLC4/NAIP5/6 inflammasome." (PMID 29717015, 2018). "The presence of the TLR5*aa02 was associated with increased susceptibility to Bartonella (adjusted p = 0.023): 41.2% animals with the allele were infected, compared to 26.8% infection among voles without it." (PMID 29849060, 2018). "Interestingly, in corneal epithelial cells, TLR5 activation, through flagellin exposure, confers protection against infection development, increasing the innate protective function of the corneal epithelium." (PMID 28796783, 2017). "Therefore, this offers potential as an intervention in reducing Th1‐mediated immunopathology during infection by TLR5‐stimulating bacteria." (PMID 26036767, 2015). "We have previously reported the association of variation in TLR5 with survival in melioidosis regardless of site of infection and here show that the association holds in respiratory disease." (PMID 25232720, 2014). "In addition our study reveals elevated TNF and CXCL2 at 24 hours post-infection in Nlrc4−/−/Tlr5−/− mice compared to Nlrc4−/− and WT mice." (PMID 23937571, 2013). "However, following infection of alveolar macrophages from TLR-5-/- mice with flagellated salmonella and flagellated PA, IL-1β production was still detectable." (PMID 24312669, 2013). "Our results indicate that Salmonella evasion of caspase-1 dependent flagellin recognition is critical for establishing infection and that evasion of TLR5 and caspase-1 dependent flagellin recognition helps Salmonella induce intestinal inflammation and establish a niche in the inflamed gut." (PMID 23977202, 2013). "Still, it is possible that TLR5 contributes to the response of the host when the infection worsens." (PMID 22330199, 2012). "During infection, monomeric flagellin released from bacterial flagella activates TLR5 signaling." (PMID 21901099, 2011). "To investigate the role of TLR-2 and TLR-5 during infection in more detail and to clearly distinguish this from signalling induced by the cagPAI-dependent injection of peptidoglycan and CagA, we were screening for a cell model system in which T4SS effectors cannot be injected." (PMID 21573018, 2011). "Additionally, TLR5 was upregulated as an upstream pathway of induced cytokines after infection." (PMID 36835242, 2023). "To explore the functions of flaB in infection, we constructed a flaB deletion mutant using a two-step recombination method, and in vitro experiments showed a significant decrease in the expression of TLR5 and inflammatory cytokines compared with wild-type cells." (PMID 34912344, 2021). "While the TLR5-mediated immune response to flagellated bacteria possibly supports robust vaginal colonization with some species, we hypothesize that this response results in protection from ascending infection with these bacteria." (PMID 33199356, 2021). "The fact that we found a striking down-regulation of FlaBs, not of FlaAs, in blood of mice and hamsters 24 h p.i with the Icterohaemorrhagiae Verdun strain, suggests that a regulation of the FlaBs expression could favor an escape from the TLR5 immune surveillance upon infection." (PMID 32849665, 2020). "Furthermore, using HEK-293-TLR5 cells we observed TLR5 signalling 2 and 4 hours post infection with P. aeruginosa (p<0.01 and p<0.001) and also after P. histicola infection (p<0.001 and p0.01) with a significant reduction at 4 hours compared to 2 hours (p<0.01)." (PMID 33031374, 2020).
infection (continued). "A slight but statistically significant upregulation of the TLR4 (2.7-fold) and TLR5 (3.4-fold) genes was observed in the spleen of S. Gallinarum-infected chickens compared to both S. Typhimurium-infected animals and uninfected control chickens at 5 days post-infection." (PMID 31998655, 2019). "Infection with ARV significantly upregulated the mRNA expression levels of TLR3 and TLR5 in host cells." (PMID 40059215, 2025). "The gene transcripts with the greatest number of shared correlations with PRRs across all three infections were PLAUR (with TLR2, RIG-I, LGP2) and SERPING1 (with TLR5, RIG-I, MDA5, and LGP2)." (PMID 40825056, 2025). "In our study, TLR5 was downregulated, while PIK3R4 was upregulated, both demonstrating a pro-infection activity." (PMID 40431739, 2025). "In leukocytes, PLAUR positively correlated with RIG-I and MDA5 which changed to TLR3, TLR6, and TLR8 with infection; PLAU, on the other hand, lost its correlation with TLR4 and TLR5 with COVID19." (PMID 40825056, 2025). "In contrast, TLR1, TLR3 and TLR5, expression was significantly downregulated, whereas TLR6 remained unchanged throughout the infection period." (PMID 41305370, 2025). "Here, we observed higher TLR2, TLR4, TLR5, TLR6, TLR8, TLR9, Myd88, NLRP3, ASC, and TNF-α mRNA expression at seven weeks after infection by S. mansoni in BALB/c and C57BL/6 mice compared to Swiss mice." (PMID 38896633, 2024). "In P. leopardus, TLR5, NOD2, and NLRP3 were all notably induced in the spleen and liver from 6 to 12 h or 24 h post-infection, and the predicted protein structures of three genes were similarly to those of mammals or other fishes." (PMID 39450165, 2024). "Toll-like receptor 5 (TLR5) is a specific receptor for bacterial flagella and plays an extremely important role in intestinal anti-infection immunity." (PMID 38188180, 2024). "The expressions of TLR3 and TLR4 were increased by infection with different ZIKV strains, and the expression of TLR5 appeared unaffected 2 days after infection." (PMID 36834929, 2023). "Goldfish during infection by the oviparous monogenean Dactylogyrus intermedius expressed high TLR4, TLR5, TLR20 and TLR22 in gills, head kidney, liver and spleen." (PMID 37759598, 2023). "During STm infection, LAP induced by flagellin-TLR5 activation in zebra fish macrophages delivers antimicrobial activity." (PMID 37425656, 2022). "Our study is the first to report on difference in TLR5, CXCL17, CCL26, IL1RL2, or IL3RA levels in sexes during infection." (PMID 36171541, 2022). "The results showed that after 24 hours of infection with UPEC CFT073, the expression of TLR4, TLR5 and myeloid differentiation Factor 88 (MyD88) mRNA in the 5637 (HTB-9) bladder epithelial cells increased significantly." (PMID 36506014, 2022). "In that study, one SNP was found located within the TLR10 gene (TLR10_292 SNP), while in the current study five SNPs were found but in the TLR5 and TLR9 genes instead, also in Corriedale sheep but under natural infection." (PMID 36140716, 2022). "Similar to TLR5 gene expression, secretion levels of IL-8 and TNF-α proteins from FICEs were increased significantly after infection with flagellins (p <0.05)." (PMID 34912344, 2021). "Some found that, during infection of murine macrophages, TLR2, TLR5, and TLR9 are required for an optimal cytokine response." (PMID 34280250, 2021). "Compared to the SISP model, significant changes were only observed for TLR5 and TLR8 mRNA expression by IPEC-J2 cells after C83901 infection, while upregulated TLR8 transcripts were also found in HB101 stimulated IPEC-J2 cells." (PMID 31221216, 2019). "Infection with S. Typhimurium and S. Dublin led to a significant downregulation of TLR2, TLR3, TLR4, TLR5, and TLR7 in chicken macrophages HD11, whereas only a slight downregulation of TLR3 and TLR7 genes was observed in the S. Gallinarum infection group." (PMID 31998655, 2019).
infection (continued). "In in vivo infection of 1-week-old chicken, a significant upregulation of the TLR4 and TLR5 genes in the spleen was observed in S. Gallinarum-infected chickens, but not in S. Typhimurium-infected chicken at 5 days post-infections." (PMID 31998655, 2019). "Keratinocyte infection with ∆fliC (Fla−) or triple mutant strains (ΔfliCΔxcpQΔpscF; Fla−/T2SS−/T3SS−) or with wild-type strain in presence of TLR5 blocking antibody resulted in significantly reduced mRNA expression and secreted levels of chemokines." (PMID 30070169, 2018). "In comparison with wild-type bacteria, infection with the complemented PA14 ΔflgK pUCP19-flgK and PA14 ΔpopB pUCP19-popB strains restored to varying degrees the protein levels of TLR4, TLR5, NLRC4, caspase-4 and mature IL-1β and IL-18." (PMID 28469996, 2017). "Transfection with TLR5 duplex A or duplex B siRNA attenuated TLR5 protein levels in HBE cells, following infection with HRV or PA, alone or in combination, compared to the control siRNA." (PMID 28489911, 2017). "In our study, expression of TLR4, TLR5, NLRC4, caspase-4, and matured IL-18 and IL-1β cytokines was induced in hCFs after infection with P. aeruginosa wild-type strains." (PMID 28469996, 2017). "The transcription of TLR1, TLR5 and TLR7 then rose again to a certain extent at the chronic stage of infection (T3)." (PMID 27661612, 2016). "The capacity of distinct flagellar serotypes to differentially activate TLR5, as demonstrated in this study, indicates an unanticipated mechanism by which different ExPEC isolates may elicit various inflammatory responses in septic individuals and during other infections." (PMID 27303721, 2016). "A recent study demonstrated that infection of monocyte-derived macrophages with a low-passage clinical strain of HCMV resulted in the upregulation of several TLRs, including TLR5, and expression of NF-κB via the MyD88 signaling pathway." (PMID 27182601, 2016). "Our results showed that F. hepatica infection significantly downregulated the mRNA expression of TLR1, TLR5, TLR6, TLR7 and TLR10 in PBMC at the acute stage of infection (T2)." (PMID 27661612, 2016). "Consistent with previous reports, B. thailandensis upregulated expression of TLR1 and TLR2 by two h post-infection, and increases in TLR1, TLR2, TLR3, TLR4, and TLR5 mRNA expression were observed by eight h post-infection." (PMID 23675544, 2013). "Conversely at 24 hours post infection, TNF levels were consistently enhanced in Nlrc4−/−/Tlr5−/− mice when compared to Nlrc4−/− or WT mice." (PMID 23937571, 2013). "Our primary finding is that TLR5 and NLRC4 mediate different roles in the inflammatory response to Lp flagellin in an aerosolized infection model." (PMID 23937571, 2013). "Here, we explored the involvement of TLR-2 and TLR-5 in THP-1 cells and HEK293 cell lines (stably transfected with TLR-2 or TLR-5) during infection with wild-type H. pylori and isogenic cagPAI mutants." (PMID 21573018, 2011). "Recruitment of TLR5‐dependent immune cells via the CCL2/CCR2 pathway is critical to the development of functional CD4+ T‐cell‐mediated immunity, which helps control bacterial colonization and decreases the degree of infection." (PMID 41457476, 2026). "Severity of infection measured by the 8-category ordinal scale (OS), where 1 is not hospitalized and 8 is death, positively correlated with platelet-TLR3 and leukocyte-TLR5, while leukocyte-TLR7 showed an inverse correlation." (PMID 40825056, 2025). "We identified 6 hub genes (IL1R1, CD163, TLR5, LY96, MMP9, and IRAK3) and 4 target miRNAs (miR-34a-5p, miR-103-3p, miR-107, and miR-124-3p) that affect the pathophysiological processes of T2DM and CS through ion transport, immune response, and infection." (PMID 40922361, 2025). "Interestingly, seven weeks post infection, this pattern shifted, as BALB/c and C57BL/6 upregulated the expression of TLR2, TLR5, TLR8, TLR9, and MyD88 mRNA." (PMID 38896633, 2024).
infection (continued). "Pretreatment of IPEC-J2 cells (on insert membranes) followed by a 2 h infection with ETEC resulted in decreased mRNA levels for IL-1β, TLR5 (P < 0.001), and MyD88 (P < 0.05), but increased mRNA levels for IL-8, TNF-α (P < 0.001), and IL-6 (P < 0.01) compared to the control group of IPEC-J2 cells." (PMID 37875712, 2024). "The data revealed strong TLR5 activation upon infection with the 22 cagPAI-positive H. pylori, but not upon infection with the 6 cagPAI-negative H. pylori strains." (PMID 39627817, 2024). "Although the relative level of TLR4 mRNA was significantly down-regulated (p < 0.0001) in L26-treated cells compared with the ST infection, the TLR5 mRNA expression in L26-treated cells was without significance." (PMID 36556320, 2022). "At 7th day post challenge, TLR5, TLR7, il6, il1b, and IL12B were still highly expressed, suggesting that TLR may play a role in both early and late stages of infection." (PMID 36439120, 2022). "The lack of differential expression of other TLR genes in this study is in contrast to a previous study of transcriptomic response of ovine PBMC conducted by our group, where TLR1, TLR5, TLR6, TLR7 and TLR10 were downregulated in PBMC at the acute stage of infection." (PMID 34616397, 2021). "We demonstrate that productive infection of macrophages can be altered by TLR signaling in response to purified ligands and bacterial coinfection, with TLR2- and TLR5-mediated signaling activating HIV-1 and TLR3- and TLR4-mediated signaling repressing HIV-1 replication in MDMs." (PMID 33472928, 2021). "However, the flagellum is also recognized by toll-like receptor 5 (TLR5) or intracellular NLRC4 as a PAMP, thereby limiting bacterial establishment of an infection." (PMID 32960172, 2020). "Our results of the in vivo analyses performed in blood and in organs suggest that TLR5 does not play a central role in the control of leptospires, neither during the acute nor during the chronic phase of infection in a murine model." (PMID 32849665, 2020). "In contrast, gene expression levels of TLR4 and TLR5 in all the tested tissues were unaffected by either NDV strains infection (data not shown)." (PMID 30070070, 2019). "A recent study identified flagellin functioning via the TLR5/NFkappaB pathway as a key UPEC virulence factor responsible for increased production of host-defense peptides, such as BD2, which mediate protection of urogenital tissues from infection." (PMID 31069177, 2019). "This probably reflects expression of some TLRs that are triggered by EPEC PAMPs such as LPS or flagellin (e.g. TLR4, TLR5), but this signaling is inhibited by TTSS effectors upon infection with the wt EPEC, but not by the TTSS-deficient escV mutant." (PMID 28671993, 2017). "After 6 h of hCFs infection with wild-type PAO1 and PA14, significant levels of TLR4, TLR5, NLRC4, native form of caspase-4 and IL-1β and IL-18 mature-formed proteins were detected by western blot with quantification of protein densitometry ratios relative to endogenous β-actin." (PMID 28469996, 2017). "In contrast, treatment with ligands of TLR-2 or TLR-5 did not affect viral capture (lanes 2–3) but led to an increased productive infection of IL-4 DCs (lanes 2–3)." (PMID 28426803, 2017). "Since we are utilizing an intracellular infection method, it is possible that this co-culture system does not yield adequate extracellular bacteria levels for proper TLR5 activation." (PMID 26367386, 2015). "TLR5 in human gastric epithelial cell lines recognizes flagellin, which induces NF-κB activation and the expression of several chemokines, mainly IL8 and GRO-α, which attract neutrophils to the infection site." (PMID 23755130, 2014). "In order to investigate the effect of statins on the expression of infection-responsive, immunomodulatory genes, 5 genes previously shown to be induced during P. aeruginosa infection were selected for analysis; KLF2, KLF6, IL-8, TLR5 and CCL20." (PMID 25010049, 2014).